MARK2 (microtubule affinity regulating kinase 2)
Description:
Serine/threonine-protein kinase. Involved in cell polarity and microtubule dynamics regulation. Phosphorylates CRTC2/TORC2, DCX, HDAC7, KIF13B, MAP2, MAP4 and RAB11FIP2. Phosphorylates the microtubule-associated protein MAPT/TAU. Plays a key role in cell polarity by phosphorylating the microtubule-associated proteins MAP2, MAP4 and MAPT/TAU at KXGS motifs, causing detachment from microtubules, and their disassembly. Regulates epithelial cell polarity by phosphorylating RAB11FIP2. Involved in the regulation of neuronal migration through its dual activities in regulating cellular polarity and microtubule dynamics, possibly by phosphorylating and regulating DCX. Regulates axogenesis by phosphorylating KIF13B, promoting interaction between KIF13B and 14-3-3 and inhibiting microtubule-dependent accumulation of KIF13B. Also required for neurite outgrowth and establishment of neuronal polarity. Regulates localization and activity of some histone deacetylases by mediating phosphorylation of HDAC7, promoting subsequent interaction between HDAC7 and 14-3-3 and export from the nucleus. Also acts as a positive regulator of the Wnt signaling pathway, probably by mediating phosphorylation of disheveled proteins (DVL1, DVL2 and/or DVL3). Modulates the developmental decision to build a columnar versus a hepatic epithelial cell apparently by promoting a switch from a direct to a transcytotic mode of apical protein delivery. Essential for the asymmetric development of membrane domains of polarized epithelial cells. Phosphorylates UBAC2 at 'Ser-223' during ER stress or starvation-induced autophagy, promoting UBAC2 dimerization and interaction with GABARAP to mediate ER-phagy.
Synonyms: EMK-1; Par-1b; Par1b; EMK1; PAR-1; MRD76
Tractability: Small molecule: a structure with a bound ligand is known; a high-quality ligand is known; it belongs to a druggable protein family. Antibody: its Gene Ontology location is reachable by antibodies, with high confidence; UniProt places it where antibodies can reach, with medium confidence; the Human Protein Atlas places it where antibodies can reach. PROTAC: it is named in the literature on targeted protein degradation; ubiquitination databases record sites on it; its protein half-life has been measured; a small molecule that binds it is known.
Target class: Protein Kinase; Kinase; CAMK protein kinase group; CAMK protein kinase MARK subfamily; CAMK protein kinase CAMK1 family; Enzyme
Gene: Protein-coding gene on chromosome 11 (63,838,923 to 63,911,020, forward strand). Ensembl gene ENSG00000072518.
Subcellular location: Cell membrane; Cytoplasm; Lateral cell membrane; Cytoplasm, cytoskeleton; Cell projection, dendrite
Subcellular location (Human Protein Atlas): Plasma membrane; Cytosol; Nucleoplasm
Gene Ontology:
Molecular function: ATP binding; cadherin binding; magnesium ion binding; protein binding; protein serine kinase activity; protein serine/threonine kinase activity; RNA binding; tau-protein kinase activity; protein kinase activator activity; tau protein binding; protein kinase activity
Biological process: establishment of cell polarity; establishment or maintenance of epithelial cell apical/basal polarity; intracellular signal transduction; positive regulation of neuron projection development; protein phosphorylation; regulation of axonogenesis; regulation of microtubule cytoskeleton organization; autophagy of mitochondrion; axon development; establishment or maintenance of cell polarity regulating cell shape; microtubule cytoskeleton organization; mitochondrion localization; neuron migration; protein autophosphorylation; regulation of cytoskeleton organization; regulation of neurofibrillary tangle assembly
Cellular component: actin filament; cytoplasm; cytosol; dendrite; lateral plasma membrane; membrane; microtubule bundle; plasma membrane; mitochondrion; cytoskeleton
Genetic constraint (gnomAD): Loss-of-function variants: 15 observed, 80.6 expected, observed/expected ratio (o/e) 0.19, 90% interval 0.12 to 0.29. The upper end of that interval is the gene's LOEUF score, 0.29, which puts it in group 1 of 6, group 1 being the genes least tolerant of losing a copy. Missense variants: 606 observed, 1,033.3 expected, observed/expected ratio (o/e) 0.59, 90% interval 0.55 to 0.63. Synonymous variants: 374 observed, 394.82 expected, observed/expected ratio (o/e) 0.95, 90% interval 0.87 to 1.03.
Homologues: Orthologues: macaque MARK2 (99% identical), dog MARK2 (99% identical), pig MARK2 (99% identical), rabbit MARK2 (99% identical), rat Mark2 (98% identical), mouse Mark2 (97% identical), guinea pig MARK2 (97% identical), chimpanzee MARK2 (85% identical), tropical clawed frog mark2 (84% identical), zebrafish mark2b (72% identical), zebrafish mark2a (70% identical). Paralogues in human: MARK1 (65% identical), MARK3 (61% identical), MARK4 (53% identical).